LAPTM4B (lysosomal protein transmembrane 4 beta)
Description:
Required for optimal lysosomal function. Blocks EGF-stimulated EGFR intraluminal sorting and degradation. Conversely by binding with the phosphatidylinositol 4,5-bisphosphate, regulates its PIP5K1C interaction, inhibits HGS ubiquitination and relieves LAPTM4B inhibition of EGFR degradation. Recruits SLC3A2 and SLC7A5 (the Leu transporter) to the lysosome, promoting entry of leucine and other essential amino acid (EAA) into the lysosome, stimulating activation of proton-transporting vacuolar (V)-ATPase protein pump (V-ATPase) and hence mTORC1 activation. Plays a role as negative regulator of TGFB1 production in regulatory T cells. Binds ceramide and facilitates its exit from late endosome in order to control cell death pathways.
Synonyms: LC27; LAPTM4beta
Tractability: Antibody: UniProt places it where antibodies can reach, with high confidence; its Gene Ontology location is reachable by antibodies, with high confidence; UniProt predicts a signal peptide or a membrane-spanning region. PROTAC: UniProt records ubiquitination sites on it; ubiquitination databases record sites on it.
Gene: Protein-coding gene on chromosome 8 (97,775,057 to 97,853,013, forward strand). Ensembl gene ENSG00000104341.
Subcellular location: Endomembrane system; Late endosome membrane; Cell membrane; Cell projection; Lysosome membrane; Endosome membrane; Endosome, multivesicular body membrane; Endosome, multivesicular body lumen
Subcellular location (Human Protein Atlas): Golgi apparatus
Gene Ontology:
Molecular function: ceramide binding; kinase binding; phosphatidylinositol bisphosphate binding; protein binding; ubiquitin protein ligase binding
Biological process: endosome organization; endosome transport via multivesicular body sorting pathway; negative regulation of lysosomal protein catabolic process; negative regulation of transforming growth factor beta1 production; regulation of lysosomal membrane permeability; regulation of lysosome organization
Cellular component: cell projection; early endosome; endosome; late endosome membrane; lysosomal membrane; lysosome; multivesicular body membrane; multivesicular body, internal vesicle; plasma membrane; endomembrane system; endosome membrane; membrane
Genetic constraint (gnomAD): Loss-of-function variants: 15 observed, 13.83 expected, observed/expected ratio (o/e) 1.08, 90% interval 0.72 to 1.65. The upper end of that interval is the gene's LOEUF score, 1.65, which puts it in group 6 of 6, group 1 being the genes least tolerant of losing a copy. Missense variants: 205 observed, 183.59 expected, observed/expected ratio (o/e) 1.12, 90% interval 1 to 1.25. Synonymous variants: 79 observed, 70.85 expected, observed/expected ratio (o/e) 1.12, 90% interval 0.93 to 1.34.
Homologues: Orthologues: chimpanzee LAPTM4B (99% identical), macaque LAPTM4B (99% identical), rabbit LAPTM4B (94% identical), mouse Laptm4b (92% identical), pig LAPTM4B (86% identical), guinea pig LAPTM4B (86% identical), rat Laptm4b (82% identical), tropical clawed frog laptm4b (81% identical), zebrafish laptm4b (71% identical), Drosophila melanogaster CG14767 (34% identical). Paralogues in human: LAPTM4A (45% identical), LAPTM5 (27% identical).
Diseases named in the same sentence as LAPTM4B in open-access papers:
LAPTM4B is named in the same sentence as 71 diseases in open-access papers, as found by Europe PMC text mining. Sharing a sentence is not in itself a finding about the gene and the disease. The quoted sentences say what the papers report.
breast carcinoma (32 papers, 2012 to 2025). "LAPTM4B is tetratransmembrane lysosomal protein that is overexpressed and associated with poor prognosis in various malignancies including breast cancer, gallbladder cancer, ovarian cancer, HCC, gastric cancer and cervical cancer." (PMID 30940109, 2019). "The current study provides an evidence of close association of HIF-1α, MDR1 and LAPTM4B expression with tumor stage, metastasis and chemotherapy treatment in breast cancer patients." (PMID 30746305, 2019). "Stratifying according to cancer types proposed that LAPTM4B polymorphism significantly increased the risk of breast cancer, gastrointestinal cancer, gynaecological cancer, liver cancer, lung cancer, and lymphoma (data not shown)." (PMID 30255662, 2018). "Stratification by cancer types suggested that LAPTM4B polymorphism is associated with the risk of breast cancer, gynaecological cancer, gastrointestinal cancer, liver cancer, lung cancer, and lymphoma." (PMID 30255662, 2018). "In further subgroup analyses, we found that the LAPTM4B polymorphism was associated with HB or PB study design, liver cancer, lung cancer, breast cancer, GC, and GIC." (PMID 24746178, 2014). "Recent studies showed that the amplification of LAPTM4B was associated with breast cancer recurrence and chemotherapy resistance." (PMID 23469012, 2013). "By PCR and qRT-PCR analysis, we revealed LAPTM4B*2 allele had higher level of LAPTM4B expression compared with LAPTM4B*1 allele both in breast cancer cell lines and tissues." (PMID 22984585, 2012). "By investigating the relationship between LAPTM4B genotype and clinicopathological variables of breast cancers, we found a strong association between LAPTM4B genotypes and histopathologic grade and lymph node metastasis in breast cancer patients." (PMID 22984585, 2012). "To evaluate the prognostic power of LAPTM4B polymorphism in breast cancer, we evaluated LAPTM4B genotype with respect to breast relapse-free survival and overall survival." (PMID 22984585, 2012). "The results of qRT-PCR analysis indicated that LAPTM4B*2 was associated with the higher level of LAPTM4B expression compared with the LAPTM4B*1 in both breast cancer cell lines and breast cancer tissues." (PMID 22984585, 2012). "In conclusion, our data demonstrated that allele LAPTM4B*2 was associated with breast cancer susceptibility." (PMID 22984585, 2012). "We then studied the effects of LAPTM4B polymorphisms on the susceptibility of breast cancer in a case-control study." (PMID 22984585, 2012). "In this study, we investigated the association between LAPTM4B polymorphism and its expression in both breast cancer cell lines and tissues." (PMID 22984585, 2012). "This study aimed to investigate the polymorphism of LAPTM4B in breast cancer by analysis the correlation of LAPTM4B genotype with breast cancer susceptibility, clinicopathologic features and prognosis." (PMID 22984585, 2012). "Patients carrying LAPTM4B*2 allele indicated 1.176-fold higher risk of developing breast cancer than those carrying LAPTM4B*1 (P<0.001, OR = 1.176, 95%CI = 1.082–1.278)." (PMID 22984585, 2012). "Previous studies had shown that the LAPTM4B gene was amplified in breast cancers, and demonstrated that amplification of LAPTM4B was associated with poor tumor response to anthracycline treatment and recurrence in women with primary breast cancer." (PMID 22984585, 2012). "We found that the allelic frequencies of the LAPTM4B*2 allele were 32.69% in the breast cancer group and 20.85% in the control group, representing a significant difference between these two groups." (PMID 22984585, 2012). "Association analysis between HIF-1α, MDR1 and LAPTM4B expression in breast cancer blood specimens." (PMID 30746305, 2019).
breast carcinoma (continued). "A recent report showed that AP4 promotes oncogenic phenotype and drug resistance in breast cancer through the regulation of a novel oncogene, lysosomal-associated protein transmembrane-4 beta (LAPTM4B), and induces prostate cancer proliferation though l-plastin regulation." (PMID 31616474, 2019). "In a further step, strategies should be developed to determine whether the detection of LAPTM4B in combination with other molecules is of diagnostic and prognostic value in assessing breast carcinoma cases." (PMID 28476037, 2017). "The allele *2 of LAPTM4B was found to be the risk factor of the certain tumors, such as breast carcinoma, colon carcinoma, hepatocellular carcinoma and gastric carcinoma, and LAPTM4B *2 was associated with poor prognosis of breast carcinoma, colon carcinoma and hepatocellular carcinoma." (PMID 25689860, 2015). "Two studies researched the relationship of the LAPTM4B polymorphism with lung and breast cancers, respectively, and they may lack power of statistical analysis." (PMID 24746178, 2014). "Therefore, allele*2 was associated with higher level of LAPTM4B expression in breast cancer cell lines." (PMID 22984585, 2012). "Our findings suggested that LAPTM4B*2 was a risk factor for the development of breast cancer." (PMID 22984585, 2012). "LAPTM4B*2 may be a potential predicative marker for the susceptibility, progression and metastasis of breast cancer." (PMID 22984585, 2012). "Odds ratio analysis showed that LAPTM4B*1/2, *2/2 and LAPTM4B (*1/2+*2/2) were associated with a significant increased risk of breast cancer compared with LAPTM4B*1/1 (OR = 1.328, 95% CI = 1.106–1.595; OR = 1.147, 95% CI = 1.046–1.257; and OR = 1.413, 95% CI = 1.169–1.707, respectively)." (PMID 22984585, 2012). "LAPTM4B*2 is a risk factor associated with breast cancer susceptibility and poor prognosis." (PMID 22984585, 2012). "We found that LAPTM4B*2 was associated with an increased risk for breast cancer." (PMID 22984585, 2012). "Therefore, allele *2 was also associated with relative higher level of LAPTM4B expression in breast cancer tissues." (PMID 22984585, 2012). "LAPTM4B gene is mapped to chromosome 8q22.1 and encodes an integral membrane protein with four transmembrane regions and is upregulated in various solid tumor tissues associated with poor prognosis, including breast cancer, NSCLC, ovarian cancer, HCC, gastric cancer, and PDAC." (PMID 36506911, 2022). "In addition, LAPTM4b is overexpressed in breast cancers compared with normal breast tissue, and it is more highly expressed in more advanced cancers, indicating that it is associated with breast cancer progression." (PMID 30103560, 2018). "This proposed that LAPTM4B*2 allele may play a vital role in the development of breast cancer." (PMID 22984585, 2012). "In human squamous cell carcinoma and breast cancer cells, stable overexpression of LAPTM4B induced sensitivity to caspase-3 activation in response to treatment with anthracyclines or paclitaxel." (PMID 40231269, 2025). "The results were similar to the previous study, which exhibited that LAPTM4B promoted the entry of cells from the G1 into the S phase in breast cancer." (PMID 40092987, 2025). "For example, LAPTM4B knockdown breast cancer cells showed an effective increase in sensitivity to chemotherapeutic drugs such as doxorubicin and zoerythromycin." (PMID 40231269, 2025). "The set of selected genes was composed of a group of angiogenesis-related genes (VEGF, PDGF, ANG-1, and PF-4) and genes that have been previously associated with carcinogenic or metastatic processes in breast cancer (WASF3, LAPTM4B, TPM3, and TAC1)." (PMID 37176055, 2023). "Several studies have shown that LAPTM4B overexpression is associated with tumorigenesis and metastatic progression in different cancers, such as hepatocellular carcinoma (HCC), breast cancer, ovarian carcinoma, and gastric cancer." (PMID 37176055, 2023).
breast carcinoma (continued). "Taken together, this study extends the findings about the serum levels of LAPTM4B in breast cancer patients." (PMID 36506911, 2022). "The present study is aimed at understanding the clinical significance of serum LAPTM4B in breast cancer (BC)." (PMID 36506911, 2022). "In breast cancer, overexpression of LAPTM4B leads to the sequestration of anthracycline, delaying its concentration in the nucleus, thereby inducing anthracycline resistance and ultimately breast cancer recurrence and metastasis." (PMID 32651973, 2021). "In breast cancer, silencing of LAPTM4B and YWHAZ gene sensitized tumor cells to anthracyclines, while overexpression of these genes induced drug resistance." (PMID 32127952, 2020). "It is reported that AP4 can up-regulate the expression of LAPTM4B to promote cell growth, migration, invasion, and cisplatin resistance in breast cancer." (PMID 31419940, 2019). "PI3K/AKT signaling pathway participated in LAPTM4B-promoting tumor progression and multidrug resistance in hepatocellular carcinoma, breast cancer and prostate cancer." (PMID 30940109, 2019). "Our recent efforts demonstrated that transcription factor AP4 positively regulates LAPTM4B to promote cell growth, metastasis and chemotherapy resistance in hepatocellular cancer and breast cancer." (PMID 30940109, 2019). "Previously, the overexpression of LAPTM4B has been studied in serum of breast cancer patients compared to healthy controls." (PMID 30746305, 2019). "Correlation of HIF-1α, MDR1, and LAPTM4B expression with clinico-pathological features of Breast cancer." (PMID 30746305, 2019). "Amplification of LAPTM4B, which contributes to chemotherapy resistance and recurrence of breast cancer and other solid tumors was over-expressed in our TKI-resistant CML cases." (PMID 30100996, 2018). "A multivariate Cox analysis identified LAPTM4B over-expression as an independent prognostic marker in breast cancer." (PMID 28476037, 2017). "Further analysis revealed that breast cancer patients with high levels of LAPTM4B protein expression had worse OS and PFS rates." (PMID 28476037, 2017). "In conclusion, our findings indicate for the first time that LAPTM4B, VEGF, and survivin protein expression is significantly associated with various clinicopathological characteristics and prognosis in breast cancer patients." (PMID 28476037, 2017). "The analysis revealed that the lipid transport related genes LAPTM4B and NDRG1 are coamplified in breast cancer patients, and identified genes potentially cooperating with LAPTM4B in breast cancer progression." (PMID 27711123, 2016). "The phenomenon illustrated the tumor heterogenicity between LAPTM4B genotype and its function, which discriminates with that in hepatocellular carcinoma, breast cancer and etc." (PMID 27391361, 2016). "In breast cancer, overexpression of LAPTM4B-35 and 8q22 amplification were contributed to de nove chemoresistance to anthracyclines and are permissive for metastatic recurrence." (PMID 25849595, 2015). "Recently, upregulated LAPTM4B expression was also found in many other malignant tumors, such as breast cancer, pancreatic cancer, and gallbladder carcinoma (GBC)." (PMID 24746178, 2014). "Our study identified the core promoter region responsible for constitutive expression of LAPTM4B and clarified that CREB1 played an important role in LAPTM4B transcriptional regulation in human breast cancer cells." (PMID 23469012, 2013). "In this study, a series of 5′-deleted constructs which generated from LAPTM4B promoter region were transiently transfected into breast cancer cell lines MCF7, T-47D and ZR-75-1 that expression LAPTM4B." (PMID 23469012, 2013). "Explicit mechanism of LAPTM4B transcriptional regulation will help us explicate the overexpression of LAPTM4b mRNA in breast cancer and understand the relationship between LAPTM4B gene and other proteins." (PMID 23469012, 2013).
breast carcinoma (continued). "The LAPTM4B gene is amplified in many breast cancers and its amplification is related to breast carcinoma recurrence." (PMID 22509374, 2012). "The LAPTM4B gene is amplified in breast cancer and its amplification is related to breast carcinoma recurrence." (PMID 22984631, 2012). "To further prove the role of LAPTM4B*2 in breast cancer, we investigated the LAPTM4B genotypes with PCR assays in 208 breast cancer patients and 211 healthy controls." (PMID 22984585, 2012). "The expression levels of LAPTM4B in breast cancer tissues and breast cancer cell lines were determined by quantitative reverse-transcription PCR (qRT-PCR) analysis." (PMID 22984585, 2012). "In breast cancer patients, genotype *2 of the LAPTM4B gene had both shorter disease-free survival and shorter overall survival by the Kaplan-Meier method." (PMID 22984585, 2012). "The relationship between LAPTM4B genotype and clinicopathological variables as well as prognosis of breast cancer was also analyzed statistical." (PMID 22984585, 2012). "In this study, we first investigated the LAPTM4B genotypes in breast cancer cell lines and breast cancer tissues." (PMID 22984585, 2012). "In contrast, doxorubicin-induced apoptosis was significantly increased in LAPTM4B knockdown breast cancer cells, suggesting that LAPTM4B might play a role in inhibiting cell survival in breast cancer." (PMID 40231269, 2025). "Based on our mechanism study of LAPTM4B, transcription factors and microRNA could bind to LAPTM4B promoter regions to regulate its expression and exert oncogenic effects in breast cancer." (PMID 36506911, 2022). "In breast cancer, LAPTM4B could predict lymph node metastasis and induce the aggressiveness of breast cancer cells." (PMID 32558212, 2020). "In addition, LAPTM4B played critical roles in tumorigenesis and tumor metastasis in hepatocellular carcinoma, ovarian cancer, breast cancer and cervical cancer." (PMID 30940109, 2019). "Northern blots revealed an overexpression of LAPTM4b mRNA in breast cancer." (PMID 23469012, 2013). "It has been reported that LAPTM4B protein is significantly up-regulated in a wide variety of cancers including hepatocellular carcinoma, extra-hepatic cholangiocarcinoma, breast cancer, endometrial carcinoma, cervival carcinoma and ovarian cancer as well as gallbladder carcinoma." (PMID 22984631, 2012). "Notably, elevated LAPTM4B levels contribute to chemotherapy resistance in breast cancer." (PMID 40092987, 2025). "Furthermore, knockdown of LAPTM4b in two cancer cell lines known to overexpress LAPTM4b15, 16, the breast cancer MDA-MB-231 and the hepatic carcinoma HepG2 lines, which also express high levels of endogenous LAT1, led to a marked reduction in S6K1 phosphorylation." (PMID 25998567, 2015). "We found that LAPTM4B (*1/2+ *2/2) genotypes are significantly associated with histopathologic grade (p = 0.0027) and lymph node metastasis (p = 0.0322) in breast cancer patients, but not with age, pathological type, tumor size, ER status, PR status, or C-erbB2 status." (PMID 22984585, 2012). "Most of LAPTM4B investigations focus on cancer research, several cohort studies reported LAPTM4B is upregulated in various tumours, including NSCLC, breast cancer and leukaemia." (PMID 39753521, 2025). "Furthermore, we have revealed that transcription factor AP-4 and microRNA-132-3p could bind to LAPTM4B protomer regions to regulate breast cancer cell proliferation and metastasis and assist drug assistance in vitro and vivo through c-myc, EMT, and PI3K-AKT signal pathways." (PMID 36506911, 2022). "In breast cancer and HCC, LAPTM4B also contributes to tumor metastasis and cell aggressiveness, and is associated with clinical features such as lymph node metastasis." (PMID 32558212, 2020). "In case of breast cancer, there were 51 patients having high expression of HIF-1α, MDR1 and LAPTM4B while 17 patients were those having low expression of all the three genes." (PMID 30746305, 2019).